STRIP2 (striatin interacting protein 2)
Description:
Calmodulin-binding scaffolding protein which is the center of the striatin-interacting phosphatase and kinase (STRIPAK) complexes. STRIPAK complexes have critical roles in protein (de)phosphorylation and are regulators of multiple signaling pathways including Hippo, MAPK, nuclear receptor and cytoskeleton remodeling. Different types of STRIPAK complexes are involved in a variety of biological processes such as cell growth, differentiation, apoptosis, metabolism and immune regulation. Required in the regulation of cell morphology and cytoskeletal organization.
Synonyms: FAM40B; KIAA1170; FAR11B
Tractability: PROTAC: ubiquitination databases record sites on it.
Gene: Protein-coding gene on chromosome 7 (129,434,392 to 129,488,399, forward strand). Ensembl gene ENSG00000128578.
Subcellular location: Cytoplasm
Subcellular location (Human Protein Atlas): Cytosol
Gene Ontology:
Molecular function: protein-macromolecule adaptor activity
Biological process: cytoskeleton organization; negative regulation of hippo signaling; regulation of hippo signaling
Cellular component: cytoplasm; FAR/SIN/STRIPAK complex; cytosol
Genetic constraint (gnomAD): Loss-of-function variants: 75 observed, 98.7 expected, observed/expected ratio (o/e) 0.76, 90% interval 0.63 to 0.92. The upper end of that interval is the gene's LOEUF score, 0.92, which puts it in group 3 of 6, group 1 being the genes least tolerant of losing a copy. Missense variants: 861 observed, 1,033.2 expected, observed/expected ratio (o/e) 0.83, 90% interval 0.79 to 0.88. Synonymous variants: 390 observed, 403 expected, observed/expected ratio (o/e) 0.97, 90% interval 0.89 to 1.05.
Homologues: Orthologues: chimpanzee STRIP2 (99% identical), macaque STRIP2 (99% identical), pig STRIP2 (98% identical), dog STRIP2 (98% identical), rabbit STRIP2 (96% identical), guinea pig STRIP2 (96% identical), rat Strip2 (96% identical), mouse Strip2 (96% identical), zebrafish strip2 (71% identical), tropical clawed frog strip2 (69% identical), Drosophila melanogaster Strip (49% identical), Caenorhabditis elegans farl-11 (41% identical). Paralogues in human: STRIP1 (70% identical).
Diseases named in the same sentence as STRIP2 in open-access papers:
STRIP2 is named in the same sentence as 19 diseases in open-access papers, as found by Europe PMC text mining. Sharing a sentence is not in itself a finding about the gene and the disease. The quoted sentences say what the papers report.
lung adenocarcinoma (9 papers, 2020 to 2026). A carcinoma that arises from the lung and is characterized by the presence of malignant glandular epithelial cells. "Other group reported that the mutants of truncated STRIP2, which were found in lung adenocarcinoma and uterine carcinoma, loss the ability to bind with PPP2CA and drove cell contraction, underlying their role in cancer." (PMID 32754603, 2020). "Similarly, reduced expression of STRIP2 was associated with a higher level of immune response in lung adenocarcinoma." (PMID 38201504, 2023). "Expression of STRIP2 has also been shown to be positively correlated with phosphorylated (p) Akt, p-mTOR, and N-cadherin, while being negatively associated with protein levels of E-cadherin in lung adenocarcinoma cells." (PMID 38201504, 2023). "It had been reported that STRIP2 has been shown to promote cell growth and migration in lung adenocarcinoma, however, the molecular mechanism for the promotion of NSCLC progression remains enigmatic." (PMID 36639675, 2023). "Research further highlighted STRIP2 in drug resistance in lung adenocarcinoma via regulating cellular immune responses." (PMID 38201504, 2023). "This manuscript revealed a significantly increased expression of mRNA and protein of STRIP2 in lung adenocarcinoma compared with the adjacent normal tissues." (PMID 35774125, 2022). "In addition, the lncRNA TMPO-AS1/let-7c-5p/STRIP2 axis has acted as a crucial role in lung adenocarcinoma progression and served as an unfavorable survival and tumor infiltration inflation markers." (PMID 36639675, 2023). "In summary, STRIP2 is a promising prognostic factor, and its future application may help determine the optimal treatment strategy for lung adenocarcinoma." (PMID 35774125, 2022). "Strip2, another scaffolding protein in the STRIPAK complex, is also reported to play roles in lung adenocarcinoma, smooth muscle, embryonic stem cells, and inner ear HCs." (PMID 33889175, 2021). "Employing 117 machine learning algorithm combinations, we develop a robust five-gene prognostic signature (FAM83A, RHOV, CPS1, STRIP2, SLC2A1) for lung adenocarcinoma (LUAD) with area under the curve values of 0.692, 0.688, and 0.614 for 1-, 3-, and 5-year overall survival, respectively." (PMID 42062606, 2026). "But the role of STRIP2 in lung adenocarcinoma (LUAD) has not been discovered clearly." (PMID 35774125, 2022).
lung carcinoma (4 papers, 2020 to 2024). "Results suggest that upregulated STRIP2 levels are associated with poor clinical outcomes in patients with lung cancer." (PMID 35774125, 2022). "Collectively, these results suggest that STRIP2 was upregulated in lung cancer and that high expression levels of STRIP2 were associated with poor outcomes in lung cancer patients." (PMID 35774125, 2022). "We also found that STRIP2 expression was associated with gender, pathological stage and lymph node metastasis in patients with lung cancer, which was statistically significant." (PMID 31901223, 2020). "Depletion of STRIP2 increases cells migration of MD Anderson-Metastatic Breast-231 cells and reduces proliferation, invasion, and migration of non-small-cell lung cancer cells, while overexpression of STRIP2 in human lung cancer cells causes enhanced proliferation, invasion, and migration." (PMID 38999976, 2024). "Results confirmed that STRIP2 was significantly increased in lung cancer cell lines, especially in A549 and H1975 cells." (PMID 35774125, 2022). "Then, we determined the prognostic values of STRIP2 in 4 independent GEO cohorts of lung cancer samples." (PMID 35774125, 2022). "Immunohistochemistry (IHC) results also confirmed that the upregulation of STRIP2 protein expression in lung cancer tissue compared to non-cancerous tissue." (PMID 35774125, 2022).
breast carcinoma (3 papers, 2018 to 2020). "Isoform 2 of STRIP2 has been proposed to antagonize the function of STRIP1 to promote breast cancer metastasis." (PMID 30622739, 2019).
heart failure (2 papers, 2016 to 2024). Inability of the heart to pump blood at an adequate rate to meet tissue metabolic requirements. "In searching for novel candidate genes involved in the pathophysiology of heart failure, we identified a 834 amino acid protein, FAM40B/KIAA1170/Strip2, which we termed Myoscape (myocardium-expressed, calcium channel-associated protein)." (PMID 27122098, 2016). "In the search for new potential candidate genes for heart failure and human cardiomyopathies, we recently discovered a previously uncharacterized protein, striatin-interacting protein 2 (Strip2), which we called "myocardium-enriched, calcium channel–associated protein" (Myoscape)." (PMID 38579991, 2024).
prostate carcinoma (2 papers, 2014 to 2020). A carcinoma that arises from epithelial cells of the prostate gland. "Besides, according to a recent study, silencing of STRIP2 also decreased cell migration in prostate cancer." (PMID 31901223, 2020).
colorectal cancer (1 paper, 2022). A primary or metastatic malignant neoplasm that affects the colon or rectum. "We found that colorectal cancer (CRC) patients with higher STRIP2 levels had shorter overall survival, disease-specific survival, and progression survival." (PMID 35774125, 2022).
gastric cancer (1 paper, 2022). A primary or metastatic malignant neoplasm involving the stomach. "Increased STRIP2 has been observed in many cancers and is correlated with poor prognosis and unfavorable clinicopathological characteristics in gastric cancer and breast cancer cells." (PMID 35774125, 2022). "A previous study found that STRIP2 expression predicts prognosis in gastric cancer." (PMID 35774125, 2022).
lung squamous cell carcinoma (1 paper, 2022). "We found that STRIP2 was more highly expressed in LUAD and lung squamous cell carcinoma (LUSC) tumor tissues than in normal lung tissue." (PMID 35774125, 2022).
cancer (9 papers, 2014 to 2025). A tumor composed of atypical neoplastic, often pleomorphic cells that invade other tissues. "There is little but strong evidence to demonstrate the connection between STRIP2 and immune cell infiltration in cancer." (PMID 35774125, 2022). "We also found that STRIP2 expression in paired cancer tissues and adjacent normal tissues in pan-cancer employed TCGA datasets." (PMID 35774125, 2022). "High expression of STRIP2 implicates neoplastic growth, metastasis, chemoresistance, and shorter survival time in various human cancers." (PMID 35774125, 2022). "We found that STRIP2 levels were significantly higher in 12 of the 18 cancers compared with normal tissue." (PMID 35774125, 2022). "Results show that STRIP2 was increased in 19 of the 33 cancers compared with normal tissue." (PMID 35774125, 2022). "Therefore, future studies of Strip2, using human pluripotent stem cells and human cancer cells would be very helpful to evaluate the importance of our studies for human therapeutic application." (PMID 36335090, 2022). "However, the potential molecular mechanisms of STRIP2 in cancer progression need to be explored in further studies." (PMID 35774125, 2022). "STRIP1, STRIP2, and STRN3 have been identified as regulators of actomyosin, while MST3 and MST4, members of GCKIII kinases, regulate cancer cells migration." (PMID 38999976, 2024). "Hence, STRIP2 may have significant effects in several biological courses, including cell growth, differentiation, and development of vascular and neural function of cardiac disease and cancer." (PMID 31901223, 2020). "In cancer cells, STRIP1, STRIP2, and STRN3 regulate cell migration and metastasis by negatively influencing MST3 and MST4 kinases, which act through the ezrin-radixin-moesin family proteins to promote the actomyosin machinery by phosphorylating PP1 and PPP1R14A-D." (PMID 38999976, 2024). "In addition, it was also indicated that high STRIP2 expression was positively associated with positive lymph node metastasis, poor tumor differentiation, positive cancer thrombus and advanced stage of patients with NSCLC, suggesting that STRIP2 may play an oncogenic role in NSCLC tumorigenesis." (PMID 36639675, 2023). "Additionally, genes such as EEF1A2 (protein synthesis and cancer cell survival), RAMP2 (cardiovascular homeostasis), PLAGL1 (cell growth suppression and differentiation activation), and STRIP2 (stem cell differentiation and cell morphology regulation) were also suppressed." (PMID 40427555, 2025).
tumor (6 papers, 2017 to 2024). "Knockdown of STRIP2 suppressed tumor growth and metastasis in vitro and in vivo, while STRIP2 overexpression obtained the opposite effect." (PMID 36639675, 2023). "Taken together, these data suggest downregulation of STRIP2 reduces tumor growth and metastasis in vivo." (PMID 36639675, 2023). "After 5 weeks, downregulation of STRIP2 significantly suppressed tumor growth and mass compared with those in the control group." (PMID 36639675, 2023). "We further determined the prognostic values of STRIP2 in various clinical subgroups, namely, the pathological stage, tumor-node-metastasis (TNM) stage, gender, age, race, and smokers." (PMID 35774125, 2022). "Given that immune checkpoints play a crucial role in tumor immunosuppression, we analyzed the correlation between STRIP2 expression and that of the immune checkpoint-related genes in LUAD using Pearson’s correlation analysis." (PMID 35774125, 2022). "Our data highlight the crucial role of STRIP2 in tumor initiation, progression, clinical outcome, and immune infiltration in LUAD." (PMID 35774125, 2022). "STRIP2 expression was explored across tumor types in the TCGA database and GETx, followed by paired-difference analysis." (PMID 35774125, 2022). "Striatin‐interacting protein 2 (STRIP2), also called Fam40b, has been reported to regulate tumor cell growth and migration." (PMID 31901223, 2020). "We identified 9 genes whose increased expression was significantly associated with tumor size in female LC patients of which four code for MAPK signaling molecules (DUSP4, FGL1, TXNRD1, PLA2G4E), three for oncogenes (KRT16, STRIP2 and TNS4), tumor suppressor cystatin 5, and NQO1." (PMID 38245882, 2024). "Therefore, in this study, we detected the connection between STRIP2 and prognosis and immune infiltration in tumor samples of LUAD patients." (PMID 35774125, 2022). "Besides, the correlation between STRIP2 expression and tumor immune infiltration as well as immune checkpoints were analyzed by the ssGSEA method." (PMID 35774125, 2022). "Striatin interacting protein 2 (STRIP2) is a core component of the striatin-interacting phosphatase and kinase (STRIPAK) complexes, which is involved in tumor initiation and progression via the regulation of cell contractile and metastasis." (PMID 36639675, 2023). "Striatin-interacting protein 2 (STRIP2), also called Fam40b, has been reported to regulate tumor cell growth." (PMID 35774125, 2022). "Our findings indicated that STRIP2 acted as a crucial oncogene in LUAD and was correlated with unfavorable survival and tumor infiltration inflation." (PMID 35774125, 2022). "First, although we explored the correlation between STRIP2 and immune infiltration in LUAD patients, there is a lack of experiments to validate the function of STRIP2 in the tumor microenvironment regulation of LUAD." (PMID 35774125, 2022). "These HLA-A24 ligands were possibly overexpressed in tumor samples and were therefore chosen as nonmutated TAA candidates of CRC111, which comprised peptides encoded by the KLK8, DEFA3, STRIP2, MMP1, FSCN1, TBX15, and PHLDA1 genes." (PMID 34185709, 2021).
STRIP2 also shares sentences with these, for which no sentence is quoted: lymph node metastasis (2 papers); non-small cell lung carcinoma (2); cardiac disease (1); cardiomyopathies (1); cerebral cavernous malformation (1); melanoma (1); metastatic colorectal cancer (1); psychosis (1); uterine carcinoma (1).